CCDC90B (coiled-coil domain containing 90B)
Synonyms: MDS011; MDS025
Tractability: Antibody: UniProt predicts a signal peptide or a membrane-spanning region. PROTAC: ubiquitination databases record sites on it; its protein half-life has been measured.
Gene: Protein-coding gene on chromosome 11 (83,259,081 to 83,286,390, reverse strand). Ensembl gene ENSG00000137500.
Subcellular location: Mitochondrion membrane
Subcellular location (Human Protein Atlas): Mitochondria
Gene Ontology:
Molecular function: protein binding
Cellular component: mitochondrion; mitochondrial membrane
Genetic constraint (gnomAD): Loss-of-function variants: 14 observed, 19.67 expected, observed/expected ratio (o/e) 0.71, 90% interval 0.47 to 1.11. The upper end of that interval is the gene's LOEUF score, 1.11, which puts it in group 4 of 6, group 1 being the genes least tolerant of losing a copy. Missense variants: 169 observed, 152.78 expected, observed/expected ratio (o/e) 1.11, 90% interval 0.98 to 1.26. Synonymous variants: 63 observed, 51.95 expected, observed/expected ratio (o/e) 1.21, 90% interval 0.99 to 1.5.
Homologues: Orthologues: chimpanzee CCDC90B (99% identical), macaque CCDC90B (93% identical), guinea pig CCDC90B (91% identical), mouse Ccdc90b (87% identical), dog CCDC90B (86% identical), pig CCDC90B (85% identical), rat Ccdc90b (85% identical), rabbit CCDC90B (81% identical), zebrafish ccdc90b (57% identical), tropical clawed frog ccdc90b (55% identical). Paralogues in human: MCUR1 (48% identical).
Diseases named in the same sentence as CCDC90B in open-access papers:
CCDC90B is named in the same sentence as 8 diseases in open-access papers, as found by Europe PMC text mining. Sharing a sentence is not in itself a finding about the gene and the disease. The quoted sentences say what the papers report.
Azoospermia (2 papers, 2022 to 2025). Absence of any measurable level of sperm,whereby spermatozoa cannot be observed even after centrifugation of the semen pellet. "Additionally, EDDM3B and LYZL1 were linked to spermatogenic failure, EDDM3B and CCDC90B with azoospermia, and EDDM3B with oligoasthenoteratozoospermia." (PMID 40497989, 2025). "Thus, the present study, in relation to the individual previous studies, aims to identify SPA17, PPP1R36, AURKA, TRIP13, PLK4, CCDC90B, and CCDC91 genes as important biomarkers of both teratozoospermia- and azoospermia-associated infertility in men." (PMID 36292606, 2022). "In the present study, we integrated four datasets, i.e., two for teratozoospermia and two for azoospermia, and successfully identified two genes, CCDC90B and CCDC91, which are commonly affected in both teratozoospermia and azoospermia." (PMID 36292606, 2022). "However, the CCDC90B and CCDC91 genes emerged as the most prominent markers common to both teratozoospermia and azoospermia as confirmed by all three analyses, i.e., Network Analyst, ExAtlas, and GEO2R." (PMID 36292606, 2022). "Therefore, it can be said that CCDC90B and CCDC91 genes could be the potential common biomarker candidates in the pathospermic conditions of both teratozoospermia and azoospermia." (PMID 36292606, 2022).
cerebral aneurysms (1 paper, 2024). "Given the limited research on CCDC90B, further studies are needed to elucidate its mechanism of action in cerebral aneurysms." (PMID 39087007, 2024). "Overall, our findings suggest that CCDC90B, tRNA PusA, and MRM3 may be common risk factors for cerebral aneurysms (ruptured and unruptured), while AIF1 and NAGS are specifically associated with an increased risk of aSAH, unrelated to uIA." (PMID 39087007, 2024). "The results suggest that CCDC90B, tRNA PusA, and MRM3 may be common risk factors for cerebral aneurysms (ruptured and unruptured), while AIF1 and NAGS are specifically associated with an increased risk of aSAH, unrelated to uIA." (PMID 39087007, 2024).
Infertility (1 paper, 2022). "However, CCDC90B and CCDC91 genes were identified as the most notable markers and they might play significant roles in the diagnosis and treatment of these two infertility conditions, paving the way to targeted therapy to cure these forms of male infertility." (PMID 36292606, 2022).
oculoauricular syndrome (1 paper, 2022). "Diseases associated with CCDC90B include oculoauricular syndrome and osteochondrosis." (PMID 36292606, 2022).
CCDC90B also shares sentences with these, for which no sentence is quoted: male infertility (1 paper); oligoasthenoteratozoospermia (1); Osteochondrosis (1); teratozoospermia (1).